LOXL2 (lysyl oxidase like 2)
Diseases named in the same sentence as LOXL2 in open-access papers (continued):
Sharing a sentence is not in itself a finding about the gene and the disease.
liver fibrosis (continued). "For instance, it has been reported that selective targeting of LOXL2 could suppress hepatic fibrosis progression and contribute to its reversal, and more excitingly, the clinical trial has been announced online." (PMID 32024063, 2020). "Indeed, previous studies in rodent models have indicated that LOXL2 inhibition can ameliorate liver fibrosis, thus highlighting its therapeutic potential." (PMID 32296422, 2020). "Although the CCl4 model recapitulates some of the histological features of liver fibrosis, it was important to determine whether LOXL2/LOXL3 enzymatic functions were also important for crosslink formation in a more physiologically relevant model." (PMID 30536539, 2019). "In addition, LOX and LOXL2 were also found to be elevated in liver fibrosis and were associated with increased deposition of collagen around the hepatocytes." (PMID 29125826, 2017). "In addition, immunotherapies that aim to enhance MoMF levels and/or reparative activity are already being clinically pursued and could have a synergistic effect with the anti-LOXL2 mAb presented here on the recovery process from liver fibrosis." (PMID 32296422, 2020). "Therefore, LOXL2-driven collagen crosslinking during liver fibrosis may impede the collagenase activity of MoMFs and their reparative behavior." (PMID 32296422, 2020). "While the anti-LOXL2 mAb had a modest impact on collagen deposition, PAT-1251 robustly and dose-dependently reduced liver fibrosis as assessed by both histological analysis of collagen deposition and biochemical analysis of hepatic hydroxyproline content." (PMID 41385725, 2026). "LOX proteins (LOX, LOXL1, LOXL2, LOXL3, and LOXL4) are extracellular copper‐dependent enzymes and have been identified as potential therapeutic targets in liver fibrosis." (PMID 38853023, 2024). "Tremendous effort has been put into defining the biological functions of LOXL2 in remodeling extracellular matrix (ECM) and the cross-linking of collagen in liver fibrosis." (PMID 37328872, 2023). "To investigate the role of MSC-ex in LOXL2 regulation, we injected MSC-ex directly into the liver using a mouse model of CCl4-mediated liver fibrosis." (PMID 37328872, 2023). "MSC-ex efficiently inhibits LOXL2 secretion of activated HSC and collagen crosslinking and suppresses liver fibrosis progression." (PMID 37328872, 2023). "In serial sections of hepatic fibrosis, we also found that the expressions of YAP and LOXL2 were pathologically correlated before and after MSC-ex action." (PMID 37328872, 2023). "Several reports implicate LOXL2 in ECM buildup and stabilization during liver fibrosis through crosslinking of structural proteins such as type I and III collagens and elastin." (PMID 32296422, 2020). "A previous study performed in a model of TAA-induced experimental liver fibrosis has explored the specific contribution of LOX and LOXL2 to fibrotic matrix stabilization utilizing specific blocking mAbs (M64 and AB0023, respectively)." (PMID 32296422, 2020). "The results presented here generate a direct link between LOXL2-governed ECM crosslinking and the impaired accessibility and scar-degrading activity of Ly6Chi monocyte-derived MoMFs in the context of liver fibrosis." (PMID 32296422, 2020). "Upon LOXL2/LOXL3 inhibition, liver fibrosis was reduced during CCl4 stimulus and STZ‐high fat diet induced NASH." (PMID 30536539, 2019). "Longitudinal studies of hepatic fibrosis, including ongoing trials of simtuzumab in NASH and advanced liver fibrosis, will contribute to the understanding of the function of LOXL2 in fibrosis progression and portal hypertension." (PMID 28480218, 2017). "Additionally, miR-27-3p has the potential to ameliorate liver fibrosis by reducing YAP expression, thereby inhibiting Lysyl oxidase-like 2 (LOXL2) and subsequently suppressing HSCs activation." (PMID 39195573, 2024).
liver fibrosis (continued). "Considering its diverse induction pathways and functions, it is more reasonable to regard LOXL2 levels as a pathophysiological biomarker along a novel axis, rather than as a marker in the context of liver fibrosis." (PMID 38740815, 2024). "Because activated hepatic stellate cells (HSC) are the primary source of collagen in established liver fibrosis, we sought to test whether HSC-activated myofibroblast functions as the cellular target of MSC-ex for anti-LOXL2 therapies." (PMID 37328872, 2023). "MSC-ex reduced YAP-activated LOXL2 expression by releasing miR-27b-3p, inhibiting liver fibrosis, which indicates that MSC-ex may represent a new strategy for treating liver fibrosis." (PMID 37328872, 2023). "PXS-5153A, a dual LOXL2/LOXL3 inhibitor, reduced disease severity and improved liver function by diminishing collagen content and collagen crosslinks in two rodent models of liver fibrosis." (PMID 35203484, 2022). "Recently, it has also been reported that insulin resistance can promote liver fibrosis through induction of lysyl oxidase-like 2 (Loxl2), independent of hepatic stellate cell activity." (PMID 31447675, 2019). "Similarly, the lysyl oxidase-like 2 (LOXL2) belonging to a family of five proteins involved in collagen crosslinking and stabilization is key in promoting liver fibrosis and limiting its resolution." (PMID 30002817, 2018). "Since PDGFRα, Col1α(I), Lrat, αSMA, and lysyl oxidase homolog 2 (LOXL2) are known as the marker for liver fibrosis, expression of these genes in non-tumor site was assessed in association with the existence of liver cirrhosis." (PMID 28465473, 2017). "Indeed, the pan-LOX inhibitor PXS-5505 and the LOXL2/3 inhibitor PXS-5153A have been proven to have anti-hepatic fibrosis properties, among which PXS-5505 is currently undergoing clinical trials (NCT04676529), indicating that LOX is still a target worth developing to treat fibrosis." (PMID 40492139, 2025). "However, selective LOXL2-blocking monoclonal antibodies failed to treat fibrosis of multiple organs, especially liver fibrosis." (PMID 37328872, 2023). "MicroRNA-29a (MIR29A) has been shown to exert a hepatoprotective effect on hepatocellular damage and liver fibrosis induced by cholestasis and diet stress, while its clinical and biological role on the activity hypoxia responsive genes including LOX, LOXL2, and VEGFA remains unclear." (PMID 34206143, 2021). "LOXL2 inhibition by Simtuzumab does not seem to be effective in liver fibrosis." (PMID 30986934, 2019). "Hence, to date, the results do not support the use of monoclonal antibody against LOXL2 for the treatment of liver fibrosis." (PMID 30986934, 2019).
hepatocellular carcinoma (44 papers, 2016 to 2025). A malignant tumor that arises from hepatocytes. "Furthermore, the upregulation of this gene, as well as CCL2, IL6, and LOXL2, has been implicated as part of the effects of cancer-associated fibroblasts in promoting progression of hepatocellular carcinoma cells." (PMID 32154227, 2020). "By activating the PI3K/AKT signaling pathway, LOXL2 can improve hepatocellular carcinoma cell infiltration and invasion and promote metastasis." (PMID 39877633, 2025). "RBP RPS7 binds to the 3′ UTR of LOXL2 mRNA and stabilizes it, further promoting hepatocellular carcinoma metastasis, which can perform as a prognostic biomarker for hepatocellular carcinoma patients." (PMID 39510185, 2024). "Increasing stiffness of ECM enhances M2 polarization and HIF-1α-induced LOXL2 expression via β5 integrin/FAK/MEK/ERK pathway of macrophage in hepatoma." (PMID 36906534, 2023). "For instance, matrix stiffness has upregulated LOXL2 through the integrin α5β1 signaling pathway in hepatocellular carcinoma." (PMID 37298730, 2023). "For example, an interaction between HIF-1α and LOXL2 (lysyl oxidase like 2) in hepatocellular carcinoma promoted cancer development, and increased angiogenesis and the EMT." (PMID 36619866, 2022). "This research is aimed at examining the expression level and prognostic value of LOXL2 in hepatocellular carcinoma and its relationship with immune infiltration and at predicting its upstream noncoding RNAs (ncRNAs)." (PMID 36254230, 2022). "The high expression of LOXL2 can also be detected in tumor tissue and serum of hepatocellular carcinoma (HCC) patients, which is related to the poor prognosis of HCC patients." (PMID 36293126, 2022). "In human hepatocellular carcinoma, the level of circulating LOXL2 (lysyl oxidase-like-2) is highly increased and correlates with metastasis occurrence." (PMID 34298680, 2021). "LOXL2 was reported to play pivotal roles in the formation of tumor microenvironment and metastatic niche in hepatocellular carcinoma." (PMID 32970930, 2020). "Next, we assessed the mRNA expression profiles in hepatocellular carcinoma HepG2 cells (named Control group), HepG2 cells transfected with plasmid LOXL2 to upregulate LOXL2 expression (named LOXL2 group), HepG2 cells treated with CoCl2 (named CoCl2 group)." (PMID 28449718, 2017). "LOXL2 has shown to promote metastasis and is correlated with poor prognosis in hepatocellular carcinoma." (PMID 28449718, 2017). "We used CoCl2 and HIF1-α knockdown to confirm that HIF1-α can induce LOXL2 expression in hepatocellular carcinoma cells in vitro." (PMID 28449718, 2017). "The purpose of our study is to explore the role of HIF-1α in progression and metastasis of hepatocellular carcinoma by promoting the expression of LOXL2 as well as the potential regulatory mechanism." (PMID 28449718, 2017). "We retrospectively evaluated the expression of HIF-1α and LOXL2 as well as the prevalence of VM among a cohort of 201 hepatocellular carcinoma specimens." (PMID 28449718, 2017). "Compared to NTA-MSCs, TA-MSCs from gastric cancer, lung cancer, pancreatic cancer and hepatocellular carcinoma (HCC) exhibit a notable elevation in cytokines like IL-6, IL-8 and TGF-β, along with genes including MMP1, S100A4, GREM1, and LOXL2, all of which are associated with tumorigenesis." (PMID 40676710, 2025). "In hepatocellular carcinoma, however, LOXL2 increases HIF1 gene expression by counteracting, in an SNAI1-dependent way, the negative action of fructose-1,6-bisphosphatase (FBP1) on HIF1 gene expression, resulting in increased aerobic glycolysis and angiogenesis." (PMID 37762708, 2023). "Furthermore, HIF1α can promote tube formation in hepatocellular carcinoma by upregulating lysyl oxidase-like 2 (LOXL2), which is involved in collagen cross-linkage during extracellular matrix (ECM) remodeling." (PMID 37298296, 2023). "Mechanistically, HIF-1α stimulates LOXL2 expression and tumor progression in hepatoma." (PMID 36906534, 2023).
hepatocellular carcinoma (continued). "Interestingly, it is also reported that LOXL2 induces vasculogenic mimicry in hepatocellular carcinoma." (PMID 35682926, 2022). "Moreover, TGFβ treatment also increases the expression of lysyl oxidase like 2 (LOXL2) in hepatocellular carcinoma cell cultures, and lysyl hydroxylase 2b (LH2b) in human synovial osteoarthritic fibroblast cultures." (PMID 33498156, 2021). "This study aimed to validate the utility of serum LOXL2 levels as a predictive biomarker for the development of hepatocellular carcinoma (HCC) in patients with hepatitis C virus (HCV) infection who achieved a sustained virological response (SVR)." (PMID 38740815, 2024). "LOXL2, a copper-dependent amine oxidase, has emerged as a promising therapeutic target in hepatocellular carcinoma (HCC)." (PMID 37511503, 2023). "Furthermore, high expression of Lysyl oxidase-like 2 (LOXL2), a matrix-remodeling enzyme that has already been associated with metastasis in hepatocellular carcinoma (HCC), in peritumoral stroma proved to be an independent prognostic factor of worse OS and DFS in patients with iCCA." (PMID 35205774, 2022). "In addition, HIF1α could promote tube formation in hepatocellular carcinoma by up-regulating lysyl oxidase like 2 (LOXL2), which is involved in collagen cross-linkage during extracellular matrix (ECM) remodeling." (PMID 31508365, 2019). "Lysyl oxidase‐like 2 (LOXL2) has shown to promote metastasis and poor prognosis in hepatocellular carcinoma (HCC)." (PMID 30506621, 2019). "TGF-β-induced up-regulation of LOXL2 in tumours, such as hepatocellular carcinoma (HCC), is critical for remodelling ECM components in the tumour microenvironment and metastatic niche." (PMID 29701666, 2018). "Additional LOXL2 treatment increases PI3K/Akt-dependent fibronectin deposition and lung metastasis in hepatoma." (PMID 36906534, 2023). "LOXL2 cross‐links ECM components and increases tissue stiffness, thereby enhancing the reorganization of cytoskeleton in hepatocellular carcinoma cells." (PMID 28556501, 2017). "TGF‐β‐mediated regulation of LOXL2 had been reported in hepatocellular carcinoma (Wong, Tse, & Huang, 2014) but had not yet been described in endothelial cells." (PMID 30387148, 2019). "FoxM1b, a transcription factor often overexpressed in human cancers, enhances LOX and LOXL2 expression by directly binding to the LOX and LOXL2 gene promoters, further activating the downstream AKT-Snail pathway and promoting EMT and hepatocellular carcinoma metastasis." (PMID 28036074, 2016). "In hepatocellular carcinoma (HCC), hypoxia-inducible factor-1α (HIF-1α) can promote VM formation through LOXL2 upregulation and eventually lead to the metastasis and progression of HCC." (PMID 38459564, 2024). "In hepatocellular carcinoma (HCC) tissues, macrophage showed an M2 polarization, and the in vitro study confirmed that a stiff matrix could strengthen the M2 polarization and induce LOXL2 expression through integrin β5-FAK-MEK1/2-ERK1/2 pathway." (PMID 36711017, 2023). "Also, LOXL2 promotes gene expression of the anti-apoptotic proteins baculoviral inhibitor of apoptosis protein (IAP) repeat-containing 3 (BIRC3) and murine double minute 2 (MDM2) in hepatocellular carcinoma." (PMID 37762708, 2023).
pulmonary fibrosis (36 papers, 2013 to 2026). Chronic progressive interstitial lung disorder characterized by the replacement of the lung tissue by connective tissue, leading to progressive dyspnea, respiratory failure, or right heart failure. "LOXL2 expression has also been detected in the serums of patients with idiopathic pulmonary fibrosis and rheumatoid arthritis-associated interstitial lung disease." (PMID 39877633, 2025). "Interestingly, increased Cu concentrations in the bronchoalveolar lavage fluid (BALF) of IPF patients have been reported, with Cu‐dependent enzymes like Lysyl Oxidase‐Like 2 (LOXL2) implicated in the pathogenesis of pulmonary fibrosis." (PMID 38872435, 2024). "Its inhibitory effect on LOXL2 activity was evaluated using LOXL2 enzymatic assays, in vitro fibrosis models with human lung fibroblasts, and in vivo models of pulmonary fibrosis, including bleomycin-treated and TGF-β1-overexpressing transgenic mice." (PMID 42198248, 2026). "Lysyl oxidase-like 2 (LOXL2) is also involved in the development of lung fibrosis and plays an important role." (PMID 41597294, 2025). "Simtuzumab, a monoclonal antibody targeting LOXL2, was tested in phase II trials for pancreatic cancer and idiopathic pulmonary fibrosis, but clinical efficacy has been limited (NCT01672853)." (PMID 40686923, 2025). "AB0023, a monoclonal antibody against human LOXL2 protein, showed efficacy in the bleomycin mouse model of lung fibrosis as well as in preclinical models of liver fibrosis and cardiac fibrosis." (PMID 39173635, 2024). "Having confirmed that the 3D spheroid model recapitulates transcriptomic and protein characteristics of fibroblast foci, we proceeded to re-evaluate the potential of LOXL2 as a therapeutic target in lung fibrosis." (PMID 39173635, 2024). "Cu can activate lung fibroblasts through the TGF-β/Smad pathway that is activated by LOXL2, leading to pulmonary fibrosis and, further, COPD." (PMID 38883186, 2024). "Previous studies have proposed that LOXL2 expression is increased within blood and lung tissue compartments of patients with lung fibrosis." (PMID 39173635, 2024). "Numerous examples of the presence of LOXL2 in serum samples of fibrosis patients have pointed to LOXL2 as a potential biomarker for idiopathic pulmonary fibrosis, cardiac fibrosis, and other pathologies." (PMID 37762708, 2023). "The expression level of LOXL2 was highly correlated with the severity of lung fibrosis, and was essential for the transition of fibroblast to myofibroblast through the TGF-beta/Smad pathway." (PMID 36830091, 2023). "LOXL2 lies upstream of Smad3 in that silencing LOXL2 inhibited the expression of pSmad3 in lung fibroblasts of bleomycin-induced pulmonary fibrosis mice." (PMID 36159334, 2022). "Moreover, inhibition of LOXL2 activity by a monoclonal antibody resulted in a significant drop in cross-linked collagen, alongside suppression of TGFβ signalling, fibroblast activation and production of growth factors and cytokines in the bleomycin model of lung fibrosis." (PMID 33498156, 2021). "Lysyl oxidase-like 2 (LOXL2), a copper-dependent monoamine oxidase, has been linked to pulmonary fibrosis." (PMID 33926483, 2021). "Unfortunately, a humanized IgG4 monoclonal antibody against LOXL2, Simtuzumab® (Gilead Sciences SA), has failed so far to achieve a significant clinical benefit in patients with idiopathic pulmonary fibrosis, NASH, or primary sclerosing cholangitis." (PMID 32296422, 2020). "Although the LOXL2 gene has been most widely studied in cancer, it has recently attracted interest for its role in fibrotic diseases such as idiopathic pulmonary fibrosis and liver fibrosis during non-alcoholic steatohepatitis." (PMID 32824630, 2020). "The relevance of LOXL2/LOXL3-selective inhibition was demonstrated in a TGF-β-driven rat model of lung fibrosis." (PMID 29966587, 2018). "A monoclonal antibody which binds and partially inhibits LOXL2, showed efficacy in the bleomycin mouse model of lung fibrosis." (PMID 29966587, 2018).